BRAF (B-Raf proto-oncogene, serine/threonine kinase)
Diseases named in the same sentence as BRAF in open-access papers (continued):
Sharing a sentence is not in itself a finding about the gene and the disease.
tumor (continued). "Conversely, the use of very sensitive molecular techniques, which could detect a minor BRAF-mutated subclone in a predominantly wild-type tumor, may not be clinically relevant as BRAF inhibitors may have opposite signaling effects in cells with mutated or wild-type BRAF." (PMID 28039443, 2017). "Furthermore, a high or perfect concordance between primary tumour and metastasis has been seen in colorectal and lung cancer and between areas with different growth patterns within lung adenocarcinomas when looking at common driver mutations such as EGFR, KRAS, NRAS and BRAF." (PMID 28347348, 2017). "Pre-clinical evidence of combinations of BRAF inhibition, MEK inhibition and anti-PD-1 antibody treatment also suggest superior anti-tumor effects compared with monotherapy." (PMID 29100459, 2017). "Melanoma antigen expression in human tumor samples was decreased at the time of tumor progression and restored with subsequent combined MEK/BRAF inhibition." (PMID 28239469, 2017). "Finally, the BRAF D594G mutation has been previously reported but data suggested that it may not have an association with aggressive tumor phenotypes." (PMID 29037218, 2017). "CNVs in tumour cells also enhance proliferation, albeit at the expense of the host; for example, copy number amplification can drive tumour growth (e.g., of FGFR2 or CDK4) or mediate drug resistance (e.g., of DHFR, KRAS or BRAF)." (PMID 28654659, 2017). "Results indicated that the tumor was wild type for RAS, BRAF, and EGFR with a high microsatellite instability (MSI-H) profile." (PMID 28903424, 2017). "In contrast, concomitant ablation of both BRAF and CRAF resulted in a complete blockage of tumour growth." (PMID 28497782, 2017). "With ongoing discussions of the use of surrogate biomarkers, the utility of liquid biopsy for sample collection, and Prof Ribas’ proposed combinations of BRAF, MEK and anti-PD1 therapy for melanoma, there seems little room for any tumour cells escaping." (PMID 29062388, 2017). "The trial failed due to unexpected tumor growth under sorafenib treatment, which was explained by paradoxical MAPK pathway activation through facilitated BRAF dimer formation in the presence of the drug." (PMID 28002790, 2017). "Previous data have suggested that the status of these genes is highly concordant between the primary tumour and metastases, with concordance rates of 92% for KRAS and 97% for BRAF." (PMID 29029407, 2017). "In patients with sequencing data from matched samples, the concordance between the primary tumour and the PM for KRAS, NRAS and BRAF was 93% (14/15), 100% (15/15) and 100% (14/14 patients) respectively." (PMID 29029407, 2017). "Data from a phase I study of the combination of BRAF/MEK inhibition and an anti-PD-1 antibody demonstrated increased levels of tumor-infiltrating T cells even post-treatment, a potential indication of increased immune activation." (PMID 29100459, 2017). "In summary, DKFZ-BT66 displayed a methylation profile similar to primary infratentorial PAs as well as to the primary tumor of origin, expressed and maintained the prototypical KIAA1549:BRAF fusion, and showed the expected MAPK activity." (PMID 28002790, 2017). "DKFZ-BT66 cells were derived from a primary PA tumor exhibiting the typical and specific KIAA1549:BRAF-fusion (KEX16BEX9)." (PMID 28002790, 2017). "Both groups showed that the efficacy of BRAF inhibitor is improved greatly in vitro when combined with an EGFR inhibitor and that this combined treatment leads to tumour regression in vivo." (PMID 28282860, 2017). "Mutant BRAF and NRAS are both known to activate the downstream kinases MEK1/2 and ERK1/2, thereby promoting tumor proliferation." (PMID 28938534, 2017). "This is reversed with BRAF or MEK inhibition, allowing low-expressing SOX10 tumor cells to be enriched in response to treatment." (PMID 29100459, 2017).
tumor (continued). "This was intriguing as it suggested that BQ788, despite enabling MITF up‐expression in the presence of BRAF inhibitor, had suppressed EDN1 expression within the tumours." (PMID 28606996, 2017). "Both BRAFV600E and BRAFnon-V600E mutant tumours were more commonly associated with the right-sided colon (44.4% and 57.1%, respectively) than the RAS/BRAF wild-type and RAS mutant tumours (13.8% and 27.5%, respectively)." (PMID 28972961, 2017). "The proto-oncogene kinases BRAF and CRAF are well-documented HSP90 client proteins that have previously been shown to be ubiquitylated and degraded in tumor cell lines treated with the HSP90 inhibitor AUY922." (PMID 28636940, 2017). "We sequenced KRAS and BRAF, assessed CpG island methylator phenotype (CIMP) frequency, and analyzed DNA mismatch repair enzyme levels using immunohistochemistry in tumor samples." (PMID 28422723, 2017). "Clinical predictions of anti-tumor activity were enabled by the use of tumor response data from three Phase 1 clinical trials testing combinations of EGFR, BRAF, and MEK inhibitors." (PMID 28649441, 2017). "Activating mutations at V600 codon of the BRAF gene, most commonly BRAFV600E, result in dramatically enhanced activity of the BRAF kinase and constitutive activation of the MAP kinase (MAPK) pathway enabling tumor growth." (PMID 28719152, 2017). "Regorafenib is a different oral MKI that potently blocks multiple protein kinases involved in tumor angiogenesis (VEGFRs 1–3, TIE2), oncogenesis (KIT, RET, RAF-1, BRAF), metastasis (VEGFR3, PDGFR, fibroblast growth factor receptor), and tumor immunity (CSF1R)." (PMID 29291014, 2017). "Similar results were observed for AML4-ALK, BRAF and DDR2 mutant or MYC amplified tumours in The Cancer Genome Atlas (TCGA) data set." (PMID 28220783, 2017). "The clinicopathologic variables compared with FBXW7 status included age, sex, race/ethnicity, site of the primary tumor, histologic grade, and KRAS, NRAS, BRAF, PIK3CA, and microsatellite instability status." (PMID 28424412, 2017). "Maertens and colleagues have identified increased activation of the PI3K/AKT/mTOR pathway in BRAF/NF1 double mutants, and a combinatorial MEK marker and mTOR inhibitor treatment has proven effective in many MEK inhibitor-resistant neoplasms." (PMID 28637487, 2017). "The dependency of KRAS mutant tumor cell lines upon CDK6 was readily apparent (rho = −0.38), but was stronger when KRAS, HRAS, NRAS, or BRAF mutant tumor cell line models were combined as a group (rho = −0.43)." (PMID 26947069, 2016). "Moreover, these guidelines also stressed the existence of accumulating evidence that patients with a BRAF mutated tumour might not benefit from anti-EGFR therapy, raising the possibility that BRAF mutation has predictive value." (PMID 27999270, 2016). "We also performed differential methylation analysis comparing the genetic alteration status, specifically looking at BRAF fusion status (n = 12) and then grouped BRAF fusion and BRAFV600E status (n = 17) of the tumours." (PMID 27229157, 2016). "There were statistically significant associations between pre-treatment plasma TIMP-1 and WHO performance status (PS), location of the primary tumor, previous adjuvant chemotherapy, KRAS and BRAF status." (PMID 27509063, 2016). "One exciting application of this approach is being tested clinically to determine which combinations of BRAF or MEK inhibitors, coupled with immunotherapy, will generate the more sustained tumor response." (PMID 26943572, 2016). "Median TTP (n=143) was longer in patients with RAS WT (13.2 (95% CI: 7.8, 17.0) months) vs MT tumours (7.3 (95% CI: 6.1, 7.6) months) and in those with RAS WT/BRAF WT (13.3 (95% CI: 9.0, 17.0) months) vs RAS or BRAF MT tumours (7.2 (95% CI: 5.7, 7.4) months)." (PMID 27764839, 2016).
tumor (continued). "This Registered Report describes the proposed replication plan of key experiments from "Kinase-dead BRAF and oncogenic RAS cooperate to drive tumor progression through CRAF" by Heidorn and colleagues, published in Cell in 2010." (PMID 26885666, 2016). "Co-treatment with a BRAF inhibitor or a PI3K inhibitor and AUY922 resulted in destruction of the tumor spheres." (PMID 27391062, 2016). "Data were analysed by tumour RAS (KRAS/NRAS) and BRAF status, and baseline amphiregulin (AREG) expression." (PMID 27764839, 2016). "Overall, the combination of BRAF and autophagy inhibition was found to be efficient in inducing tumor regression in the PLX4720-resistant tumor xenografts." (PMID 27583134, 2016). "Our findings indicate that selective BRAF inhibitor-induced AMPK phosphorylation coordinates control of autophagy and tumor chemoresistance in BRAFV600E CRC cells." (PMID 26750638, 2016). "In addition to these clinical trials not taking BRAF mutation status into account, clinical anti-tumor activity may not have been seen as a result of the pharmacokinetic properties of bortezomib." (PMID 27783987, 2016). "One recent study found that using a combination of an antibody-drug conjugate targeting EDNRB, together with small-molecule inhibitors of the MAP kinase pathway, increased anti-tumor activity in BRAF/NRAS mutant cell lines and tumor models." (PMID 27148356, 2016). "Skin toxicity of any grade occurred in 68 of 69 patients (99%) with RAS WT tumours, 71 of 74 patients (96%) with RAS MT tumours, 59 of 60 patients (98%) with RAS WT/BRAF WT tumours and 80 of 83 patients (96%) with RAS or BRAF MT tumours." (PMID 27764839, 2016). "Knowing BRAF was the target of miR-378-5p, we tested the expression of BRAF in the 47 CRC and adjacent non-tumor tissues." (PMID 25977643, 2015). "In addition, we examined clinical and molecular variables, including tumor location, adjuvant chemotherapy status, microsatellite instability (MSI), CpG island methylator phenotype (CIMP), KRAS mutation and BRAF mutation, to determine whether these characteristics act as confounding factors." (PMID 25875774, 2015). "These two antibodies in combo with BRAF/MEK inhibitors potently inhibit in vitro cell growth and tumor regrowth after drug withdrawal in an in vivo xenograft model." (PMID 26208478, 2015). "Demonstration of increased phosphorylation of BRAF and MEK proteins in patient’s tumor cell lysates or inhibition of mutant-induced MEK and/or ERK phosphorylation by BRAF inhibitors in cell culture systems was also used to define kinase-activated mutants." (PMID 26498038, 2015). "Given the impressive tumor ORR, PFS and OS, it is clear that combined BRAF and MEK inhibition improves upon and offers the maximum opportunity for those benefits in patients with MM." (PMID 26143635, 2015). "HGF secreted by stromal cells in the tumor microenvironment can activate the HGF receptor MET, initiating MAPK and PI3K signaling to confer resistance to BRAF inhibition." (PMID 25763355, 2015). "ERβ agonists also exert a tumor suppressor activity in WM115 (BRAF V600D-mutant) cells, while they fail to reduce cell proliferation in A375 and WM1552 (BRAF V600E-mutant) cells." (PMID 26225426, 2015). "Such plasticity is thought to arise through interactions between aberrant signaling events, including persistent activation of the APC/β-catenin and KRAS/BRAF/ERK pathways, and the tumor microenvironment." (PMID 25699236, 2015). "Therapeutic manipulation of the BRAF and MAPK pathway has been extensively investigated in many tumor types." (PMID 25785246, 2015). "Acquired resistance is also a major problem during treatment with BRAF or MEK inhibitors, with most patients demonstrating tumor progression within 5–7 months of the start of therapy." (PMID 26137449, 2015).
tumor (continued). "The BRAF study enrolled 20 patients with tumoral CRC BRAF mutation (comprising 10 patients with MSI tumor and 10 patients with MSS tumor) and 10 patients with tumoral CRC BRAF wild type and MSS." (PMID 25983749, 2015). "In the case of the wild-type BRAF SK23-MEL cells, both treatments induceda certain degree of delay in tumor growth, but nonetheless effects appeared quite limited, anddid not result in an improvement in survival (ILS < 20%)." (PMID 25595904, 2015). "In 52 patients, discordance between primary tumor and CTCs was 5.77% for KRAS, 3.85% for BRAF, 11.54% for CD133 rs3130, 7.69% for CD133 rs2286455 and 11.54% for PLS3 rs6643869 mutations." (PMID 25902072, 2015). "Late intervention with the BRAF inhibitor, PLX-4720, has also been observed to induce tumor regression in an orthotopic mouse model of ATC with BRAF mutant cells." (PMID 25940539, 2015). "In preclinical studies, combined treatment based on inhibition of BRAF and silencing of AKT3 was found to significantly increase suppression of tumour growth as compared to the result obtained by single agent administration." (PMID 25627962, 2015). "The clinical significance of finding a BRAF mutation in a nondominant tumor, however, is unknown." (PMID 26448939, 2015). "Given the well-established role for RAS activity in tumour cell resistance to therapy, we examined the relative contribution of the RAF family kinases BRAF and CRAF to radioresistance." (PMID 26333361, 2015). "Univariate analyses documented the lack of association between Aurora-A expression and clinicopathological parameters,including age, gender, tumor size, lymph node metastasis, histology, TNM, BRAF status and recurrences." (PMID 25807528, 2015). "As a result, the cells show activation of key signal transduction pathways, including PI3K-AKT-mTOR, BRAF-MEK-MAPK, and STAT3 that have roles in promoting tumor growth, survival, and metastasis." (PMID 25897429, 2015). "However, BRAF can promote MEK-ERK activation and tumor progression through several mechanisms, including the proposed mechanism of tumorigenesis mediated by kinase-dead BRAF that could cooperate with oncogenic RAS to induce CRAF activation and MEK-ERK signaling." (PMID 24817905, 2014). "One patient had a primary tumor that was NRAS wild type and BRAF mutant and stained homogeneously positive with VE1." (PMID 25526463, 2014). "The present study results showed that endogenous BRAF and CRAF dimerization was significantly enhanced in the tumor cells from the primary lung lesion and the peritoneal metastases in this case." (PMID 25013473, 2014). "One group II tumor, GG17, demonstrated BRAF duplication and a potential BRAF fusion, the latter on the basis of a ‘break-apart’ probe profile that showed one (normal) overlapping pair of signals and one ‘split’ pair of signals." (PMID 24529209, 2014). "Our study provided new insight into the mechanism by which miR-524-5p inhibits the MAPK/ERK pathway through the down-regulation of BRAF and ERK2, leading to prohibition of tumor growth." (PMID 25275294, 2014). "But in combination, MDM2 plus BRAF inhibition and MDM2 plus MEK inhibition elicited 89 and 93% decreases in tumor volume, respectively (p < 0.0001 for each combination vs. its respective single-agent comparators)." (PMID 24810962, 2014). "We were also interested in correlating an altered PI3K pathway and a normal PI3K pathway to the NSCLC tumor subtypes ADCA and SCC, gender, smoking status, IRS-1 G972R genotypes as well as to KRAS/BRAF status." (PMID 24500884, 2014). "As sorafenib blocks the RAF/MEK/ERK pathway to inhibit tumor angiogenesis and induce apoptosis in HCC cells, the reactivation of ERK signaling confers acquired resistance to BRAF and MEK inhibitors." (PMID 25057499, 2014).
tumor (continued). "By comparison, the use of very sensitive molecular techniques that would detect a minor BRAF-mutated subclone in a predominantly wild-type tumor may not be clinically relevant as BRAF inhibitors may have opposite signaling effects in cells with mutated or wild-type BRAF." (PMID 23976959, 2013). "Whole exome sequencing of tumor obtained at time of progressive disease did not reveal secondary BRAF or RAS mutations, but did demonstrate a somatic gain-of-function PIK3CA mutation (H1047R) as well as a CDKN2A aberration, which may have been responsible for dabrafenib resistance." (PMID 23470635, 2013). "Moreover, no relation of KRAS or BRAF mutation and clinical tumor stage was observed." (PMID 24139521, 2013). "The tumor tissues were sequenced for KIT, BRAF, NRAS, and GNAQ mutant genes and patients with amplification or overexpression of KIT were treated with Sunitinib." (PMID 23515890, 2013). "We correlated the KRAS, BRAF and PIK3CA genotypes with clinicopathological features of CRC, including primary tumour location, histological findings, and sites of metastases." (PMID 23617638, 2013). "Phosphorylation of wildtype BRAF at S602 by MLK3 is known to activate cell proliferation pathways, however BRAF V600E tumor cells proliferate independently of MLK338." (PMID 24089029, 2013). "In conclusion, the utility of the BRAF and KRAS as prognostic biomarkers depends on the MSI status and tumor location." (PMID 24073892, 2013). "To evaluate this in vivo, we tested AZD8055 and selumetinib in both a BRAF mutant (OCM1A) and GNAQ mutant (92.1) xenograft tumor model." (PMID 22808163, 2012). "Further evidence of compensatory increases in MAPK activation/growth by RAF inhibition was observed in treated BRAF-WT, RAS mutant HCT116 xenografts that displayed significantly increased tumor volumes and FDG uptake." (PMID 22651703, 2012). "This was not due to ineffective mTORC2 inhibition, but instead rebound AKT phosphorylation: while 100 nM AZD8055 inhibited AKT phosphorylation after 2 hours in all three tumor genotypes, by 24 hours AKT phosphorylation rebounded only in BRAF and GNAQ cells." (PMID 22808163, 2012). "The BRAF and KIT genotypes of the isolated CTC were then analysed; the results showed that the genotypes of the CTC differed from those of the primary tumours and metastatic lesions." (PMID 22281663, 2012). "In the xenograft model of the BRAF mutant cell line OCM1A, Western analysis of frozen tumor tissue revealed that cooperative MCL-1 downregulation and increased BIM levels were also achieved in vivo." (PMID 22808163, 2012). "The combination efficacy of BRAF inhibition and TRAIL treatment was also applied to a three-dimensional (3D) cell culture system as an in vitro tumor model where a significant apoptotic effect was recorded." (PMID 21738740, 2011). "Overall, the only independent factors predicting survival in BRAF- mutant patients in our clinic was treatment with any RAF/MEK axis targeting agent and any initial tumor regression." (PMID 22039425, 2011). "Importantly, these methylation-dependent subtypes stratify disease outcome; MSI tumours are clinically favourable, but respond poorly to 5-fluorouracil-based chemotherapy, whereas CIMP tumours have complex associations with patient outcome that may depend on MSI and/or BRAF V600E status." (PMID 21587258, 2011). "We then correlated the KRAS and BRAF genotypes with clinicopathological features of CRC, including primary tumour location, histological findings, and sites of metastases." (PMID 21285991, 2011).